TNF (tumor necrosis factor)
Diseases named in the same sentence as TNF in open-access papers (continued):
Sharing a sentence is not in itself a finding about the gene and the disease.
depression (continued). "Classical monocytes lead to ischemic lesions by producing IL-1β, IL-6, and TNF-α, which are connected with the presence of depression." (PMID 35935403, 2022). "Patients with major depressive disorder have been found to have increased proinflammatory factors such as interleukin (IL)-6, IL-1β, and tumor necrosis factor (TNF)-α." (PMID 36144545, 2022). "Compared with the non-depression group, patients with depressive symptoms had higher levels of inflammatory cytokines, including IL-1, IL-6, TNF-α, and CRP." (PMID 35757220, 2022). "One study found that the levels of proinflammatory cytokines TNF-α and IL-6 in patients with major depression increased significantly." (PMID 36364213, 2022). "A meta-analysis of 24 studies in depressed patients found that individuals with major depression had significantly higher TNF-α and IL-6 plasma concentrations in comparison to controls." (PMID 35267893, 2022). "Elevated IL-1β, IL-6, TNF-α and IL-17 levels were observed in clinical patients with pain and depression comorbidity." (PMID 35733107, 2022). "TNF is a key mediator of inflammation, and inflammation is one of the main pathological features of depression." (PMID 36496703, 2022). "Serum TNF‐α, IL‐1β, IL‐6, and IL‐17 are related to increased anxiety and depression risks to some extent in NSCLC survivors." (PMID 34697903, 2022). "For example, intravenous or subcutaneous IL-1β injection increased depression-like behavior in mice and enhanced the expression of pro-inflammatory cytokines TNF-α and IL-6 in the amygdala, which is regulated by the CORT/GR system." (PMID 36232376, 2022). "Clinical trials suggest that when the inflammation level is high initially (C-reactive protein >5 mg/dL), combined use of cytokine antagonists (e.g., TNF antagonist infliximab) and antidepressant therapy can improve the course of depression." (PMID 36619667, 2022). "Analyzing results separately for depression, mania, and mixed state, decreased TNF-alpha levels were found for each mood state." (PMID 36032249, 2022). "An association between IL-2, IL-6, IL-8, TNF-α and VEGF levels and the severity of depression have been reported." (PMID 36045388, 2022). "While not considered statistically significant following the Bonferroni corrections, MCP-1, TNF- α, and depression had potential links upon univariate analysis and should be considered candidates for evaluation in future larger studies." (PMID 35745504, 2022). "Second, TNF-α activates tryptophan- and serotonin-degrading enzyme indoleamine-2,3-dioxygenase, resulting in reduced availability of serotonin in patients with depression." (PMID 35722555, 2022). "Patients with depression often have elevated TNF-α, IL-1, IL-1β, IL-2, IL-6, IL-8, IL-17, IL-21, IL-23, C-reactive protein, and TGF-β." (PMID 35054853, 2022). "The most common cytokines associated with poor psychological outcomes involving PTSD and/or depression in the chronic mTBI population were IL-6, TNFα, IL-10, and CRP." (PMID 35053845, 2022). "Depression is also associated with elevated levels of inflammatory factors such as C-reactive protein (CRP), tumor necrosis factor-alpha (TNF-α), and interleukin 6 (IL-6)." (PMID 35360021, 2022). "The increased expression of TNF-α can induce changes in brain structure and function, leading to the development of depression." (PMID 35479322, 2022). "Corroborating this observation, higher concentrations of proinflammatory cytokines, such as IL-6 and TNF-alpha, are observed more often in patients with depression than in healthy subjects." (PMID 35237160, 2022). "Strikingly, upregulated levels of IL-6 and TNF-α in serum of patients with depression or Alzheimer’s disease were identified, suggesting a role of pro-inflammatory cytokines in promoting cognitive disorders." (PMID 36061856, 2022). "TNF-α levels have been reported to be elevated in patients with depression, unchanged, and decreased." (PMID 35722555, 2022).
depression (continued). "Studies have shown that the levels of pro-inflammatory cytokines such as interleukin-6 (IL-6) and tumor necrosis factor (TNF) in patients with depression are significantly increased." (PMID 36297505, 2022). "Increase in inflammatory cytokines (IL-1β, IL-6, and TNF-α) has also be reported in common neuropsychiatric conditions including depression and schizophrenia." (PMID 35538558, 2022). "TNF-α (β = 0.263, p < 0.001), along with sleep quality (β = 0.27, p < 0.001) and depression (β = 0.376, p < 0.001) independently predicted prenatal fatigue." (PMID 36193420, 2022). "It has been shown that sulforaphane, a potent agonist of Nrf2, ameliorated depression-like behavior in LPS-induced mice, decreased serum levels of TNF-α and IL-10, and inhibited activation of microglia." (PMID 35923544, 2022). "A previous randomised-controlled trial (RCT) in individuals with treatment-resistant depression investigated the efficacy of infliximab, a monoclonal antibody for TNF-α, in the reduction of depressive symptoms." (PMID 36085284, 2022). "Increased levels of NfL and TNF-α were related to executive dysfunction in major depressive disorder." (PMID 34637515, 2022). "Not only pro-inflammatory cytokines (e.g., IL-1β and TNF-α) were found to be dysregulated in depression patients, but also IL-1β, IL-6, TNF-α, or lipopolysaccharide (LPS) administration in animal models led to depression- and anxiety-like behaviours." (PMID 36145259, 2022). "Patients suffering from depression often display increased levels of pro-inflammatory cytokines, such as interleukin-1 (IL-1), interleukin-6 (IL-6) and tumor necrosis factor-α (TNF-α), as well as endogenous metabolites including nesfatin-1 and corticosterone." (PMID 36183107, 2022). "Numerous studies have demonstrated that TNF-α levels are elevated in patients with major depression, bipolar disorder and schizophrenia." (PMID 36145284, 2022). "Patients with depression have increased pro-inflammatory cytokines in the blood, such as interleukin-6 (IL-6), interleukin-1β (IL-1β), tumor necrosis factor-α (TNF-α) and other acute-phase proteins and C-reactive protein (CRP)." (PMID 36357867, 2022). "A meta-analysis of mean differences and variability in 5166 patients and 5083 controls showed that TNFα was significantly higher in patients with depression, confirming depression as a pro-inflammatory state." (PMID 36142325, 2022). "It has become common to treat depression according to the inflammatory mechanism and pro-inflammatory cytokines (such as IL-1 β, IL-6, and TNF-α)." (PMID 35682841, 2022). "The biomarkers assessed in the studies involving depression include IL-6 (n = 5), IL-10 (n = 4), TNF-α (n = 4), IL-1β (n = 2), CRP (n = 2), and IL-7 (n = 1)." (PMID 35053845, 2022). "A rat model of EAP complicated with depression was established and confirmed by increases in IL-1β, IL-6, and TNF-α as well as the occurrence of depressive‐like behaviors." (PMID 36250064, 2022). "The six predominant targets (TNFα, ESR1, TLR4, PTGS2, MMP9 and NOS3) have been well documented to associate with depression." (PMID 35626632, 2022). "Even in patients with chronic obstructive pulmonary disease (COPD) with depression in comorbidities there was an increase in the concentration of inflammatory markers such as IL-1 and TNF-α salivary and a decrease in salivary cortisol." (PMID 36140234, 2022). "Studies have shown that Rg1 reduced the levels of IL-1β, TNF-α, caspase-1, IL-2, IL-6 and IL-18 via the suppression of Connexin43 (Cx43) ubiquitination in depression." (PMID 36010610, 2022). "Other studies have shown an association between QoL indicators, including fatigue, anxiety, and depression levels, and increased production of proinflammatory cytokines, including IL-6 and TNF-α." (PMID 34815548, 2022). "We find that RS neurons exhibit synaptic depression in response to both dark exposure (DE) and monocular deprivation (MD), and their homeostatic recovery from depression is dependent on TNF-α." (PMID 35649371, 2022).
depression (continued). "Enormous studies have manifested increased levels of proinflammatory cytokines such as CRP, IL-1β, IL-6, and TNF-α in elderly patients with depression (and the patients underwent surgery)." (PMID 35356751, 2022). "In conclusion, this study provides support that both IL-6 and TNF-α are related to a meta-analysis derived somatic dimension of depression." (PMID 35651828, 2022). "While studies generally agree that cytokines such as IL-6 and TNF-α are correlated with depression, the role of CRP (a cytokine that generally exhibits robust correlations with depression) specifically in HIV-associated depression is a major area of debate." (PMID 35618889, 2022). "Studies have shown that depression is related to the expression of a variety of molecules, including IL-6, IL-2, IL-1β, TNF-α, and C-reactive protein (CRP)." (PMID 36010610, 2022). "This indicates that the concurrent elevation of IL-6 and TNF-α should be highly suspected of depression, while meanwhile, reminding the clinical staff to carefully observe and timely formulate innovative therapeutic strategies." (PMID 35757220, 2022). "Th17 cells participate in depression, which is activated by several cytokines, such as IL-1β, TNF-α, and IL-6." (PMID 35054853, 2022). "In conclusion, common inflammatory cytokines including TNF-α, IL-1β, and IL-17 were related to cognition impairment, anxiety, and depression in AIS patients in this study." (PMID 35239774, 2022). "It appears to be accomplished by altering the expression of depression-related factors, including IL-6, IL-18, and TNF-α to achieve antidepressant-like effects." (PMID 35795547, 2022). "Antidepressants influence unfavorable immune phenomena in depression, reducing the level of pro-inflammatory cytokines (e.g., TNF-α, IL-6), which are also pain mediators." (PMID 35955097, 2022). "SD stress has also been reported to induce depression by promoting the expression of proinflammatory cytokine genes, such as IL-1β and TNF-α, which are well-known stress markers." (PMID 36014820, 2022). "To validate that our model was successful and verify the relationship between central and peripheral cytokines and depression, we measured the mRNA expression and protein level of pro-inflammatory cytokines, including IL-6, IL-1β and TNF-α." (PMID 36357867, 2022). "In conclusion, common inflammatory cytokines including TNF-α, IL-1β, and IL-17 were related to cognition impairment, anxiety, or depression in AIS patients." (PMID 35239774, 2022). "In a meta-analysis studying inflammatory markers in depression (collecting 5166 patients with depression and 5083 healthy controls), the researchers found that IL-6, TNF-α, IL-12, IL-3, IL-18, and sIL-2R were elevated in depression group." (PMID 36408212, 2022). "TNF-α concentrations are known to be increased after acute stress, in depression and anxiety disorders/PTSD, and there is also evidence suggesting an involvement of TNF-α in noise-induced hearing loss and tinnitus." (PMID 35814090, 2022). "Baicalin significantly reduced the levels of TNF-α, IL-1β, and IL-6 in depression-like hippocampal tissues by upregulating PI3K/AKT/FOXO1 pathway and inhibiting TLR4 expression and so alleviate neuroinflammation-induced depression-like behavior." (PMID 35350754, 2022). "In the current study, we enrolled 217 NSCLC survivors to evaluate levels of TNF‐α, IL‐1β, IL‐6, and IL‐17 and their correlations with anxiety and depression." (PMID 34697903, 2022). "Maladaptive inflammatory responses to various stressors leading to elevation in pro-inflammatory cytokines such as interleukin 1β, interleukin 6, and tumor necrosis factor α is another proposed mechanism of depression." (PMID 35606688, 2022). "Depression-like behaviors are related to increased peripheral blood levels of IL-1β, IL-6, TNF, and CRP, the most reliable biomarkers of inflammation." (PMID 36278007, 2022).
depression (continued). "Pre-clinical studies focusing on different chronic pain models with comorbid depression also reported upregulation of IL-1β, IL-6 and TNF-α." (PMID 35733107, 2022). "Loss of Ninj2 inhibits oligodendrocyte development and myelination by inducing TNFα‐mediated necroptosis, impairs neuron functions, and results in depression." (PMID 34787377, 2022). "The reason behind its potential pharmacological effect is the presence of terpenoids and polysaccharides that regulate the imbalance in the microbial community to ameliorate depression and anxiety via the TNF-α/NF-κβ signaling pathway." (PMID 36499295, 2022). "In BD depression, IL-6 is the predominant cytokine, in euthymic state it is IL-4, and in manic episode it is IL-2, IL-4, IL-6, while patients with unipolar depression have mainly elevated TNF-α, IL-6 and soluble IL-2 receptor (sIL-2R)." (PMID 36294388, 2022). "Given epidemiologic relationships identified between IL-6, tumor necrosis factor (TNF)- α, and subsequent depression, levels of these pro-inflammatory cytokines were also explored as potential moderators of depressed mood response to endotoxin." (PMID 35871638, 2022). "We aimed to evaluate serum tumor necrosis factor‐α (TNF‐α), interleukin‐1 beta (IL‐1β), interleukin‐6 (IL‐6), interleukin‐17 (IL‐17) levels, and their correlations with anxiety/depression in NSCLC survivors." (PMID 34697903, 2022). "The up-regulation of TNF levels in depressed patients has been demonstrated, therefore, infliximab is used to treat depression also." (PMID 36755665, 2022). "In the present study, we discovered that high TNF-α and IL-6 were correlated with cognition impairment occurrence; high TNF-α, IL-1β, and IL-17 were correlated with anxiety or depression occurrence in AIS patients." (PMID 35239774, 2022). "Depression-like symptoms can be alleviated by increasing the expression of Nrf2/HO-1 and decreasing the expression of IL-1β, IL-6, and TNF-α in the microglial cells." (PMID 35634375, 2022). "CSF concentrations of markers such as TNF-α and IL-1β are also correlated with depression severity, and exogenous induction of inflammation can produce some core features of depression." (PMID 35618889, 2022). "Infliximab is ineffective in reducing depressive symptoms when used for treatment-resistant depression, which is significantly related to TNF levels." (PMID 36755665, 2022). "During the progression of depression, TNF impairs the synthesis of monoamine neurotransmitters and the increased accumulation of neurotoxic metabolites, thus reducing the availability of 5-hydroxytryptamine synthesis." (PMID 36325528, 2022). "Among these signaling pathways, the AGE-RAGE, vascular endothelial growth factor (VEGF), nuclear factor kappa-light-chain-enhancer of activated B cells (NF-kB) and TNF signaling pathways are highly related to depression formation and progression." (PMID 35626632, 2022). "NAC also exerts an anti-inflammatory role by decreasing various cytokines in the brain, especially IL-6, TNF-α and IL-1β, which are involved in the inflammatory mechanisms of depression." (PMID 36291336, 2022). "The M1 state of microglia is characterized by the elevated secretion of proinflammatory cytokines, including IL-1β, IL-6, and TNF-α, which trigger neuronal damage and contribute to the development of anxiety and depression." (PMID 35209199, 2022). "We performed ROC analysis to distinguish the depression of patients with different clinical characteristics according to the IL-6, TNF-α, and CRP values." (PMID 35757220, 2022). "This study aimed to examine the relationship between a psychological stressor such as major depressive disorder and an increase in pro-inflammatory cells such as IL-1, IL-6, and TNF-alpha." (PMID 35582022, 2022). "Among inflammatory markers, elevated levels of C-reactive protein, IL-6, and TNF are the most reliable markers of depression." (PMID 36619667, 2022).
depression (continued). "Plenty of studies convincingly manifested that elevated TNF-α levels existed in patients with major depressive disorder." (PMID 35757220, 2022). "Compared with healthy controls, patients with major depression have exhibit increased TNF-α and IL-1β levels both in the cerebrospinal fluid and in the peripheral blood circulation." (PMID 36052143, 2022). "On the other hand, intestinal inflammation can also act on the central system by the production of pro-inflammatory cytokines such as tumor necrosis factor α (TNF-α), thus inducing the symptoms of anxiety or depression." (PMID 35425777, 2022). "Increases in IL-6 and TNF-α levels in CSF and brain parenchyma are considered markers of central inflammation in depression in the context of a possible increased microglia activity and reduction of astrocyte and oligodendrocyte markers." (PMID 36142325, 2022). "For example, in a population of dysthymic children and adolescents, reduced levels of plasma concentrations of TNF-α were identified when compared with those with major depression." (PMID 37274848, 2022). "Pro-inflammatory cytokines such like TNF-α and IL-6 have been shown to be increased in patients with depression, and human volunteers were indeed induced anxiety and depression by the treatment with pro-inflammatory cytokine IFN-α." (PMID 35558075, 2022). "TNF-α and IL-6 are two common inflammatory cytokines involved in the neuroinflammatory response in depression." (PMID 36431060, 2022). "Here, we demonstrated that the AGE-RAGE signaling pathway was involved in CORT-induced depression and promoted the secretion of proinflammatory cytokines (IL-1β and TNFα)." (PMID 35626632, 2022). "In breast cancer patients, positive correlations have been observed between depression and inflammatory markers, such as IL-1β, IL-6, and tumor necrosis factor-alpha (TNF-α)." (PMID 36615742, 2022). "Proinflammatory cytokines, including interleukin (IL)-6 (area under the curve (AUC) = 0.76) and tumor necrosis factor (TNF)-α (AUC = 0.75), showed good performance in accurately predicting depression in patients with glioma." (PMID 35757220, 2022). "Other studies have shown that sub-anesthetic ketamine inhibited TNF-α production in multiple models and conditions, including in a rat model of endotoxin stimulus, human subjects with clinical depression, and LPS-induced inflammation in canines." (PMID 35379262, 2022). "Atorvastatin decreased depressive-like behaviors in several mouse models of depression by decreasing TNF- α, IL-1β, and NF-κB p65, or by increasing hippocampal BDNF." (PMID 35207483, 2022). "The relationship between increased levels of cytokines including tumour necrosis factor-α (TNF-α) and IL-6 and major depression disorder is now recognised." (PMID 35330292, 2022). "Previous studies demonstrated that depression-like behaviors caused by stress were dependent on HMGB1/TLR4/NF-κB and TNF-α/TNFR1/NF-κB signalling pathways in CUMS-exposed mice." (PMID 35386281, 2022). "Mechanistically, it is accepted that both depression and sickness behavior are mediated through the actions of interleukin 1 (IL‐1), interleukin 6 (IL‐6), and tumor necrosis factor α (TNFα)." (PMID 35924463, 2022). "For instance, infliximab—a TNF antagonist, surpassed placebo in depression score reduction only in the hsCRP > 5 mg/L group." (PMID 36291336, 2022). "Several previous studies have shown that anxiety-like or depression-like behaviors in db/db mice are ameliorated by the intracerebroventricular (i.c.v.)or systemic administration of a TNF-α inhibitor." (PMID 36091357, 2022). "TNF-α signaling through NF-KB has previously been shown to activate microglia and increase neuroinflammation in mice showing depression-like behaviour." (PMID 36077051, 2022). "Elevated levels of TNF-α and the ratio of kynurenine/tryptophan, indicating inflammation-induced activation of the KP, have recently been found in a subgroup of depression with more severe anhedonia and poorer treatment response." (PMID 36536364, 2022).